NECAB3 (N-terminal EF-hand calcium binding protein 3)
Description:
Inhibits the interaction of APBA2 with amyloid-beta precursor protein (APP), and hence allows formation of amyloid-beta. May enhance the activity of HIF1A and thus promote glycolysis under normoxic conditions; the function requires its ABM domain and may implicate the stabilization of the interaction between HIF1AN and APBA3.
Synonyms: APBA2BP; NIP1; SYTIP2; XB51; dJ63M2.4; dJ63M2.5; EFCBP3; STIP3
Tractability: PROTAC: ubiquitination databases record sites on it.
Gene: Protein-coding gene on chromosome 20 (33,657,087 to 33,674,463, reverse strand). Ensembl gene ENSG00000125967.
Subcellular location: Golgi apparatus
Subcellular location (Human Protein Atlas): Golgi apparatus
Gene Ontology:
Molecular function: protein binding; calcium ion binding
Biological process: protein metabolic process; regulation of amyloid precursor protein biosynthetic process; protein secretion
Cellular component: cytoplasm; endoplasmic reticulum membrane; Golgi apparatus; Golgi cis cisterna; endoplasmic reticulum; nucleus
Genetic constraint (gnomAD): Loss-of-function variants: 35 observed, 42.27 expected, observed/expected ratio (o/e) 0.83, 90% interval 0.63 to 1.1. The upper end of that interval is the gene's LOEUF score, 1.1, which puts it in group 4 of 6, group 1 being the genes least tolerant of losing a copy. Missense variants: 430 observed, 429.57 expected, observed/expected ratio (o/e) 1, 90% interval 0.92 to 1.08. Synonymous variants: 195 observed, 175.8 expected, observed/expected ratio (o/e) 1.11, 90% interval 0.99 to 1.25.
Homologues: Orthologues: chimpanzee NECAB3 (98% identical), chimpanzee NECAB3 (96% identical), macaque NECAB3 (94% identical), pig NECAB3 (79% identical), mouse Necab3 (78% identical), guinea pig NECAB3 (78% identical), rat E2f1 (77% identical), dog NECAB3 (76% identical), rabbit NECAB3 (71% identical), zebrafish necab3 (44% identical). Paralogues in human: NECAB1 (42% identical), NECAB2 (35% identical).
Diseases named in the same sentence as NECAB3 in open-access papers:
NECAB3 is named in the same sentence as 19 diseases in open-access papers, as found by Europe PMC text mining. Sharing a sentence is not in itself a finding about the gene and the disease. The quoted sentences say what the papers report.
breast carcinoma (1 paper, 2023). "However, NECAB3 was identified to be tumorigenic by promoting normoxic glycolysis in non-breast cancer cell lines." (PMID 36936429, 2023).
liver cancer (1 paper, 2023). An epithelial or non-epithelial malignant neoplasm that arises from the liver. "As expected, this study revealed that silence of NECAB3 suppressed the migration and invasion of liver cancer cells, and overexpression of NECAB3 promoted the cancer cell migration and invasion." (PMID 37215053, 2023). "The invasive ability of liver cancer cells was impaired by downregulation of NECAB3 and enhanced by increased NECAB3 (P < 0.05)." (PMID 37215053, 2023). "As expected, it was observed that overexpression of NECAB3 enhanced liver cancer cell migration and invasion, which was suppressed by downregulation of RIT1 (P < 0.05)." (PMID 37215053, 2023). "Consistent with the conjecture, results revealed that the inhibitory effect of downregulation of NECAB3 on liver cancer migration and invasion was reversed by the overexpression of RIT1." (PMID 37215053, 2023). "In conclusion, we reported the function and mechanism of NECAB3 regulating liver cancer progression for the first time." (PMID 37215053, 2023). "Knockdown of NECAB3 suppressed aggressive phenotype of liver cancer via modulating the HIF-1α/RIT1 axis, providing a possible target for liver cancer therapy." (PMID 37215053, 2023). "NECAB3 is a newly recognized regulator of cancer progression, while its role in liver cancer remains to be elucidated." (PMID 37215053, 2023). "Then, functional experiments revealed that downregulation of NECAB3 suppressed liver cancer cell migration and overexpression of RIT1 promoted cell migration (P < 0.05)." (PMID 37215053, 2023). "Results revealed that NECAB3 was highly expressed in liver cancer cells (P < 0.05)." (PMID 37215053, 2023). "Given the evidence, we speculated that NECAB3 might regulate liver cancer progression via modulating the HIF-1α/RIT1 axis." (PMID 37215053, 2023). "Given the aberrant expression of NECAB3 in liver cancer, we speculated that NECAB3 might modulate the liver cancer progression." (PMID 37215053, 2023). "Besides, downregulation of NECAB3 suppressed the migrative ability of liver cancer cell, whereas upregulated NECAB3 exerted the opposite function (P < 0.01)." (PMID 37215053, 2023). "Knockdown of NECAB3 restrained liver cancer cell migration and invasion." (PMID 37215053, 2023). "Besides, the NECAB3 expression in liver cancer cells including Huh-7, Hep3B2, Li7, and HCCLM3 and human hepatocytes was detected." (PMID 37215053, 2023). "Furthermore, NECAB3 regulated liver cancer migration and invasion through modulating RIT1 expression." (PMID 37215053, 2023). "In other words, NECAB3 regulated liver cancer migration and invasion through modulating RIT1." (PMID 37215053, 2023). "Thus, the study clarified the action of NECAB3 on liver cancer development and explored the detailed mechanism." (PMID 37215053, 2023). "It was observed that NECAB3 was significantly elevated in liver cancer tissues (P < 0.001)." (PMID 37215053, 2023). "Thus, the knockdown of NECAB3 restrained the migrative and invasive ability of liver cancer cells." (PMID 37215053, 2023). "Moreover, the in vivo experiments revealed that downregulation of NECAB3 suppressed liver cancer tumor growth, which indicated that NECAB3 may be a potential therapeutic target for treating liver cancer." (PMID 37215053, 2023). "Therefore, we inferred that the upregulated NECAB3 might regulate liver cancer progression via modulating the HIF-1α/RIT1 axis." (PMID 37215053, 2023). "Hence, we emphasized the role of NECAB3 in liver cancer tumorigenesis in this study." (PMID 37215053, 2023). "However, the action of NECAB3 on liver cancer remained elusive." (PMID 37215053, 2023). "Knockdown of NECAB3 suppressed the aggressive phenotype of liver cancer via modulating the HIF-1α/RIT1 axis, providing a possible target for liver cancer therapy." (PMID 37215053, 2023). "N-terminal EF-hand calcium binding protein 3 (NECAB3) is a new recognized regulator of cancer, while its role in liver cancer remained elusive." (PMID 37215053, 2023).
papillary kidney carcinoma (1 paper, 2016). "Interestingly, NECAB3, Mint3, and MT1-MMP were induced in three tumours (urothelial bladder cancer, papillary kidney carcinoma, liver hepatocellular carcinoma), implying that NECAB3-mediated HIF-1 activation might play some role in these cancers." (PMID 26948053, 2016).
Parkinson disease (1 paper, 2013). A progressive degenerative disorder of the central nervous system characterized by loss of dopamine producing neurons in the substantia nigra and the presence of Lewy bodies in the substantia nigra and locus coeruleus. "We were specifically drawn to a group of genes that were significantly dysregulated in blood and brain, including Necab3, Apbb2, App, Psen1, Saa1, Prkcg, Park2, Snca and Prnp, because of their involvement in neurodegenerative diseases, such as Alzheimer’s and Parkinson’s disease." (PMID 24278249, 2013).
cancer (6 papers, 2016 to 2023). A tumor composed of atypical neoplastic, often pleomorphic cells that invade other tissues. "N-terminal EF-hand calcium binding protein 3 (NECAB3) is a cancer progression regulator discovered in recent years." (PMID 37215053, 2023). "Down-regulation of NECAB3 in cancer cells was demonstrated to reduce tumorigenicity, indicating the crucial role of NECAB3 in promoting cancer development." (PMID 34900444, 2021). "Inhibition of NECAB3 in cancer cells by either expressing shRNAs or generating a dominant negative mutant reduced tumourigenicity." (PMID 26948053, 2016). "Recent studies reported that NECAB3 also exerted regulation effect on cancer." (PMID 37215053, 2023). "Up-regulation of NECAB3 in cancer cells was demonstrated to enhance tumorigenesis." (PMID 34900444, 2021). "Importantly, inhibition of NECAB3 suppresses normoxic glycolysis in cancer cells and reduces tumourigenicity." (PMID 26948053, 2016). "Taken together, the data indicate that NECAB3 is a promising new target for cancer therapy." (PMID 26948053, 2016). "Interestingly, the previous research proved that NECAB3 could activate hypoxia-inducible factor-1 alpha (HIF-1α) in cancer cells." (PMID 37215053, 2023). "Finally, targeting NECAB3, especially its monooxygenase activity, may prove useful as a cancer therapeutic strategy." (PMID 26948053, 2016). "Thus, NECAB3 seems to function distinctly from other NECABs, at least in cancer cells." (PMID 26948053, 2016). "We have recently reported that the monooxygenase NECAB3 and mTOR signalling also promote Mint3-mediated HIF-1 activation in cancer cells." (PMID 27883071, 2016). "Depletion of NECAB3 decreased the expression of HIF-1 target genes and reduced glycolysis in normoxic cancer cells." (PMID 26948053, 2016). "Using RT-PCR, we found NECAB2 and NECAB3, but not NECAB1, to be expressed in cancer cells." (PMID 26948053, 2016).
tumor (3 papers, 2016 to 2023). "Results revealed that downregulation of NECAB3 significantly suppressed tumor growth in vivo compared to the shNC group (P < 0.001)." (PMID 37215053, 2023). "GNAS-AS1 has been reported to promote tumor progression in non-small cell lung cancer (NSCLC) by altering macrophage polarization via the GNAS-AS1/mir-4319/NECAB3 axis." (PMID 35937989, 2022). "Exogenous expression of NECAB3 dominant negative mutants also decreased tumour growth to approximately 50% (N1 and H/A)." (PMID 26948053, 2016). "Besides, immunohistochemistry results revealed that NECAB3 was inhibited in tumor tissues by shNECAB3." (PMID 37215053, 2023). "NECAB3 depletion decreased subcutaneous tumour growth to approximately 40–50% of control cells." (PMID 26948053, 2016). "Similarly, NECAB3 depletion decreased tumour growth from A431 and A549 cells to a comparable extent as Mint3 depletion." (PMID 26948053, 2016). "Similarly, NECAB3 was proved to promote tumor progression of NSCLC." (PMID 37215053, 2023). "Furthermore, Western blot result showed that shNECAB3 greatly suppressed the protein levels of NECAB3, HIF-1α, and RIT1 in tumor tissues (P < 0.001)." (PMID 37215053, 2023). "Finally, we analysed expression of NECAB3, Mint3, and MT1-MMP in human tumour and normal tissues using mRNA-sequencing datasets from The Cancer Genome Atlas (TCGA)." (PMID 26948053, 2016).
neurodegenerative disease (1 paper, 2013). A disorder of the central nervous system characterized by gradual and progressive loss of neural tissue and neurologic function. "While Necab3, Apbb2, App, Psen1, Prkcg and Saa1 are associated with Aβ accumulation, Park2 and Snca are associated with protein aggregation in AD and PD, as well as other neurodegenerative diseases." (PMID 24278249, 2013).
NECAB3 also shares sentences with these, for which no sentence is quoted: autism (1 paper); chromophobe renal cell carcinoma (1); hepatocellular carcinoma (1); lung adenocarcinoma (1); lung squamous cell carcinoma (1); oesophageal cancer (1); paraganglioma (1); phaeochromocytoma (1); prostate (1); prostate adenocarcinoma (1); prostate carcinoma (1); urothelial bladder cancer (1).